NEAT1 (nuclear paraspeckle assembly transcript 1)
Diseases named in the same sentence as NEAT1 in open-access papers (continued):
Sharing a sentence is not in itself a finding about the gene and the disease.
tumor (continued). "In particular, NEAT1 inhibition by short hairpin RNAs (shRNAs) significantly enhances the effectiveness of sorafenib, leading to prompted drug-induced cell death and significantly smaller tumor mass in nude mice compared to treatment with sorafenib alone." (PMID 38960924, 2024). "By transferring exosomal NEAT1 to EC cells, an acceleration in tumor growth was observed." (PMID 39188680, 2024). "The correlation between lncRNA NEAT1 expression and tumour size was reported in 5 papers." (PMID 39139172, 2024). "Further research into NEAT1 could reveal significant insights into tumor biology, potentially leading to breakthroughs in early diagnosis and more effective treatment strategies." (PMID 39139172, 2024). "The role of NEAT1 in vivo was investigated by an intracranial tumor formation experiment in mice." (PMID 39453684, 2024). "NEAT1’s actions weave a complex regulatory web, pivotal to the tumor’s ecological dynamics." (PMID 39286016, 2024). "Furthermore, elevated NEAT1 levels have been correlated with decreased overall survival, increased likelihood of tumor recurrence, larger tumor size, and higher WHO grade." (PMID 39453684, 2024). "Therefore, targeting NEAT1 is vital to enhance the sensitivity of tumor cells to DNA-damaging agents such as PARP inhibitors." (PMID 38356722, 2024). "NEAT1‐miRNA regulatory networks play crucial roles in the regulation of tumorigenesis, in which NEAT1 may function either as an oncogene or a tumor suppressor gene." (PMID 38577722, 2024). "Furthermore, how NEAT1 dysregulation impacts the tumor transcriptome and functional pathways remains elusive." (PMID 39032650, 2024). "Similarly, there is controversy regarding the correlation between clinicopathological features such as lymph node metastasis, degree of tumour differentiation and NEAT1 expression." (PMID 39139172, 2024). "In this regulatory loop, NEAT1 targeted miR-34a and promoted autophagy to enable chemoresistance, also suggesting that miR-34a may be a tumour suppressor since the overexpression of miR-34a phenocopied NEAT1 knockdown." (PMID 36983973, 2023). "Another subcluster, NEAT1+ tumor cells, were mainly found in the SMI group." (PMID 37430270, 2023). "NEAT1 could accelerate tumor cell proliferation, migration, invasion, EMT, TNM stage, and lymph node metastasis." (PMID 37310654, 2023). "Furthermore, NEAT1 contributes to the promotion of tumor growth by hampering cytotoxic T cell-mediated immunity, primarily through the downregulation of the stimulator of interferon genes, cyclic GMP-AMP synthase." (PMID 38066437, 2023). "Notably, overexpressing NEAT1 enhances the anti-tumor effects by intensifying ferroptosis in vitro and in vivo." (PMID 37759495, 2023). "Notably, tumor specimens characterized by elevated infiltration of cytotoxic CD8 + T cells tend to display diminished levels of NEAT1 expression." (PMID 38066437, 2023). "It has been displayed that NEAT1 by sponging miR-124-3p and binding to the human antigen R (HuR) protein could stimulate tumor cell proliferation and invasion." (PMID 37310654, 2023). "Moreover, NEAT1 fosters tumor growth by reducing the expression of cyclic GMP–AMP synthase stimulator of interferon genes, which inhibits cytotoxic T cell-mediated immunity." (PMID 37161350, 2023). "NEAT1 by targeting miR-124-3p presented an essential role in tumor development." (PMID 37310654, 2023). "High expression of FOSB+, NEAT1+, or XIST+ tumor cell-associated genes such as FSTL3, VTN, PAPPA, CCN1, RRAD, and GPRIN3 may predict poor survival in patients with LUSC, suggesting that these genes act as prognosis biomarkers." (PMID 37430270, 2023). "NEAT1 was previously identified as an oncogene that promotes tumor cell proliferation." (PMID 38115130, 2023).
tumor (continued). "Besides, NEAT1 was reported to stimulate several tumor microenvironment-related genes such as MEF2D, ROCK1, WNT7A, VEGFA, PDE4B and KPNA4." (PMID 37310654, 2023). "In an interesting case, the lncRNA NEAT1 has also been identified as a tumor suppressor in AML." (PMID 37267628, 2023). "The PTC xenograft tumor model was used for investigating the role of NEAT1 in vivo." (PMID 35635748, 2022). "Exosomal NEAT1 is also able to promote tumor growth in a xenograft model of HEC-1A EC cells." (PMID 35406505, 2022). "Previous studies suggested that NEAT1 promotes tumor development by downregulating target miRNAs." (PMID 35428188, 2022). "In-vivo tumorigenesis experiments showed that NEAT1 knockdown suppressed tumor growth." (PMID 36213831, 2022). "Overexpression of NEAT1 increased tumour growth and induced the development of liver metastasis." (PMID 36434587, 2022). "NEAT1 is a lncRNA that is upregulated in many tumor tissues." (PMID 35637962, 2022). "We found that HB-derived exosomal lncRNA NEAT1 induced BMSCs to differentiate into tumor-supporting myofibroblasts by regulating the miR-132/MMP9 axis, which might benefit an innovative therapeutic strategy for the treatment of HB patients." (PMID 35300348, 2022). "However, despite ample additional in vitro evidence for the role of Neat1 in tumor initiation and progression in multiple tumor types, Neat1−/− mice are not reported to spontaneously develop tumors." (PMID 35681513, 2022). "NEAT1 participates in multiple biological pathways through a diverse group of mechanisms due to the formation of the paraspeckle, which it can influence the stability of a tumor to develop chemoresistance." (PMID 35687898, 2022). "Our findings outline the critical role of NEAT1 in ferroptosis and its regulatory mechanism, suggesting that ferroptosis induction may be a promising therapeutic strategy for tumor patients with high expression levels of NEAT1." (PMID 35338333, 2022). "Taken together, our results highlight a complex interplay involving different species of RNAs, in which miR-378a-3p displays a tumor-suppressor function in CRC-SCs by modulating lncRNAs NEAT1 and MALAT1 that are critical for CRC cell growth and metastatization." (PMID 35814429, 2022). "As expect, NEAT1 knockdown significantly inhibited tumor growth." (PMID 35123484, 2022). "Importantly, overexpression of NEAT1 increased the anti-tumor activity of erastin and RSL3 by enhancing ferroptosis both in vitro and in vivo." (PMID 35338333, 2022). "On the other hand, NEAT1 transcripts can also act as a tumour suppressor." (PMID 35457249, 2022). "However, only a handful of recent studies have established the relative abundance of the two isoforms, despite many reports suggesting that NEAT1 acts as either a tumour suppressor or oncogene, depending on this isoform ratio." (PMID 36139550, 2022). "The application of HyPro labeling in patient samples promises to be a powerful tool to understand how NEAT1 could modulate gene expression in tumours and may pave the way for the identification of novel tumour targets." (PMID 35457249, 2022). "The long noncoding RNA, NEAT1, is often dysregulated in tumours." (PMID 36139550, 2022). "Together, NEAT1 modulated the anti-tumor activity of erastin and RSL3 in HCC cells in vivo." (PMID 35338333, 2022). "Moreover, the expression of NEAT1 in tumor tissue was significantly higher than that in normal tissue." (PMID 36213831, 2022). "More specifically, the administration of CAFs that overexpress NEAT1 leads to enhanced EC tumor volume and increased proliferation capacity, as demonstrated by the elevated percentage of proliferation index marker Ki-67-immunopositive tumor cells." (PMID 35406505, 2022). "Tumor formation experiments in nude mice showed that HB-derived exosomal lncRNA NEAT1 could affect the development of HB." (PMID 35300348, 2022). "One possibility is that changes in the NEAT1 isoform ratio have tumour- or tissue-specific effects." (PMID 35457249, 2022).
tumor (continued). "Together, our data showed that miR-378a-3p may exert its tumor suppressor function modulating NEAT1 and MALAT1 lncRNA expression, though a weaker tumorigenic inhibition was observed in miR-378 restoration experiments compared to knockdown experiments." (PMID 35814429, 2022). "Therefore, knockdown of NEAT1 suppressed CRC cells tumor growth and progression with the miR-138/SLC38A1 axis, exerting an underlying strategy for CRC management." (PMID 35676702, 2022). "It has been demonstrated that hypoxia could induce the aberrant expression of lncRNAs, such as H19, HOTAIR, and NEAT1 to regulate tumor biology." (PMID 35846431, 2022). "NEAT1 knockout can reduce the proliferation, invasion, and metastasis of tumor cells." (PMID 36246567, 2022). "In AML, NEAT1 functions as a tumor-suppressor, meaning it is down-regulated in de novo AML." (PMID 36362925, 2022). "In this review, specific emphasis was placed on NEAT1's role in tumor development." (PMID 34512157, 2021). "Furthermore, silencing of NEAT1 decreased the xenograft tumor growth by decreasing MEST while up-regulating let-7 g and ATGL." (PMID 34416900, 2021). "Moreover, traditional chemotherapy combined with drugs targeting tumor stem cells provides a new strategy for the treatment of CRC patients CRC patients with high NEAT1 expression." (PMID 34938735, 2021). "Several lncRNAs with abundant expression (LRRC75A-AS1, HYMAI, NEAT1, XIST and FTX) were closely associated with tumor size, which may suggest to be biomarkers for the GIST malignancy." (PMID 34557343, 2021). "Compared with shRNA group, silence of NEAT1 reduced tumor size and weight (P<0.05)." (PMID 34837887, 2021). "However, there is little research on the relevance of tumor-derived exosomes and NEAT1 in BC development." (PMID 33820555, 2021). "Tumor samples with high levels of cytotoxic CD8+ infiltration express NEAT1 at lower levels." (PMID 34654454, 2021). "The number and size of tumor spheres decreased also upon NEAT1 knockdown." (PMID 33614649, 2021). "We also identified five lncRNAs with abundant expression (LRRC75A-AS1, HYMAI, NEAT1, XIST and FTX) were closely associated with tumor progression, which may suggest to be the biomarker for the malignancy of GIST." (PMID 34557343, 2021). "In addition, NEAT1 sponges miR-214 to regulate M2 macrophage polarization by regulating B7-H3 in multiple myeloma, which further promotes tumor immune evasion." (PMID 34654454, 2021). "NEAT1 knockdown reduced the growth of the tumor and attenuated the tumor growth induced by PTRF." (PMID 35069587, 2021). "Moreover, the combined treatment of NEAT1 siRNA3 with anlotinib remarkably decreased the tumor volume and weight compared to sole anlotinib treatment." (PMID 33982669, 2021). "However, our study also assessed the function of the NEAT1/miR-183/STAT3 axis in the MET process in metastatic tumours." (PMID 33546665, 2021). "Another interesting finding was the involvement of the NEAT1/miR-183/STAT3 axis in the MET process, which is the opposite process of the EMT and was proposed as a crucial mechanism underlying the formation of metastatic tumours." (PMID 33546665, 2021). "Moreover, RUNX2 expression was markedly elevated in tumor tissues formed by MDA‐PCa‐2b cells overexpressing NEAT1." (PMID 34459124, 2021). "Interestingly, inhibiting NEAT1 significantly inhibited tumor growth in patients with neck nodal metastasis, emphasizing its value as a therapeutic target." (PMID 34316331, 2021). "Results showed that tumor volume in the shNEAT1 group was dramatically smaller than those in the shCtrl group, and inhibiting miR-17-5p markedly reversed the inhibitory effects of NEAT1 silencing on the xenografts proliferation." (PMID 34552925, 2021). "Finally, silencing NEAT1 in murine CD8 T cells impaired tumor growth in a transplantable mouse model of HCC." (PMID 34830805, 2021).
tumor (continued). "Furthermore, NEAT1 promotes tumor growth by inhibiting cytotoxic T cell-mediated immunity through a decrease in the expression of cyclic GMP-AMP synthase stimulator of interferon genes." (PMID 34654454, 2021). "Several studies have found that lncRNA NEAT1 promotes tumor growth in a variety of malignancies." (PMID 34950596, 2021). "In the present study, we demonstrated that NEAT1 is a critical suppressor of miR-98, suggesting that the tumor suppressor roles of miR-98 might be rescued by NEAT1 inhibition." (PMID 34950596, 2021). "And the anti-tumor effect of NEAT1 on AML depended on CREBRF." (PMID 32280304, 2020). "Xenograft model was established to observe the effect of NEAT1 on tumor growth in vivo." (PMID 32336952, 2020). "Notably, NEAT1 overexpression leads to an increase in the number and dimension of PSs in tumor cells." (PMID 32630183, 2020). "Furthermore, the expression of NEAT1 can be detected in multiple tumor types and other non-tumor diseases." (PMID 33574830, 2020). "In addition, in vivo tumor formation assay was used to reveal the impacts of NEAT1 knockdown on RB progression in vivo." (PMID 33281873, 2020). "Despite the fact that a number of the functions of NEAT1 in tumours are unknown, research is beginning to show that the two 3′ processing variants, NEAT1_1 and NEAT1_2, generally have opposing effects in tumours." (PMID 33143162, 2020). "Noteworthy, we demonstrated that the plant mtr-miR-5754 and gma-miR4995 directly target the tumor-associated long non-coding RNA metastasis-associated lung adenocarcinoma transcript 1 (MALAT1) and nuclear paraspeckle assembly transcript 1 (NEAT1) in a sequence-specific manner." (PMID 33193626, 2020). "Together, these results indicated that NEAT1 knockdown weakened tumor growth in vivo." (PMID 32336952, 2020). "By being the key structural component to the paraspeckles, as well as through other means, NEAT1 interacts with gene regulatory pathways to bring about changes in gene expression that increase or decrease the ability of tumours to withstand chemotherapy and form CSCs." (PMID 33143162, 2020). "Therefore, the induction of Plxna4 expression by NEAT1 results in decreased proliferative abilities and decreased angiogenic properties of tumours, through the inhibition of VEGF." (PMID 33143162, 2020). "Additionally, the xenograft model assays demonstrated that NEAT1 knockdown suppressed tumor growth in vivo." (PMID 32336952, 2020). "Moreover, NEAT1 depletion resulted in increased expression of miR-206 (1.78-fold increase, P < 0.001) and miR-599 (1.64-fold, P < 0.001) in tumor tissues." (PMID 32336952, 2020). "Therefore, the data demonstrated that m6A of NEAT1–1 elevated the tumor growth and metastasis in mice PDX model." (PMID 33308223, 2020). "This review aims to provide an overview of the current knowledge on the involvement of NEAT1 and PSPs in DDR, which might strengthen the rationale underlying future NEAT1-based therapeutic options in tumor and neurodegenerative diseases." (PMID 32630183, 2020). "Overall, NEAT1 plays an oncogenic or a tumor suppressive role, needing further exploration." (PMID 32042268, 2020). "Results showed that tumor volume and weight were dramatically decreased by NEAT1 silencing." (PMID 33281873, 2020). "Moreover, our in vivo study found that when NEAT1 was silenced, the tumor growth was retarded, and more importantly, cytotoxic T cells were elevated." (PMID 32296457, 2020). "In our ceRNA network, NEAT1 is a tumor suppressors targeting both miR-330-3p and miR-149-5p." (PMID 32948197, 2020). "Similarly, downregulation of NEAT1 enhanced the radiation-mediated inhibition of tumor growth, which was mitigated by decrease of miR-27b-3p." (PMID 33292252, 2020).
tumor (continued). "Based on the expression changes observed in our analysis, it is tempting to speculate that NEAT1 might indeed function as a tumour suppressor in PDAC." (PMID 32727085, 2020). "In contrast to NEAT1, miR‐384 might act as a tumor suppressor and inhibit the proliferation, migration, and invasion of HCC cells." (PMID 30346062, 2019). "We also found that NEAT1 knockdown reduced the PCNA expression level in xenograft tumour model." (PMID 30407674, 2019). "Moreover, NEAT1 overexpression reduced the expression level of miR‐193a in CRC cell lines and miR‐193a expression was increased in tumour tissues derived from sh‐NEAT1 group as compared with the sh‐NC group." (PMID 30407674, 2019). "Increased expression of NEAT1 in CRC tissues indicated its tumour‐promoting role in CRC." (PMID 30407674, 2019). "NEAT1 is also involved in impairing anti-tumor drug (sorafenib) sensitivity." (PMID 31480503, 2019). "We found that the proliferation rates of tumours were lowered by NEAT1 knockdown." (PMID 30407674, 2019). "Furthermore, NEAT1 was confirmed to act as a sponge of miR‐193a, and knockdown of NEAT1 attenuated miR‐193a inhibitor‐induced tumour promoting effects and L17RD expression in CRC cells." (PMID 30407674, 2019). "The lncRNA NEAT1 promotes many tumors by functioning as an endogenous competing RNA (ceRNA) for tumor suppressor miRNAs, but whether NEAT1 sponges miRNAs to drive aggressive EC progression and chemoresistance remains unclear." (PMID 31287002, 2019). "However, the combination of NEAT1 expression knockdown and TX treatment resulted in more pronounced tumor growth suppression than TX treatment or NEAT1 expression knockdown alone, as evidenced by significant reductions in tumor volume and tumor weight." (PMID 31287002, 2019). "Accumulating evidence has shown that lncRNA might be a competing ceRNA for specific miRNAs to regulate its target genes. lncRNA NEAT1 has been reported to promote tumor progression by sponging some microRNAs." (PMID 30346062, 2019). "Our findings suggest that NEAT1 acts as an oncogene, whereas miR‐204 acts as a tumor suppressor." (PMID 30803129, 2019). "In vivo experiments were performed to investigate the effect of NEAT1 on tumor growth." (PMID 31462890, 2019). "High NEAT1 levels correlate with tumor grade, occurrence of metastasis, and an unfavorable prognosis and could therefore be a potential biomarker for OC." (PMID 30430751, 2019). "Yet some investigations manifested conflicting consequence, defining NEAT1 as a tumor suppressor." (PMID 30575330, 2019). "This reciprocal repression of miR‐384 and NEAT1 might highlight the significance of RNA‐RNA interaction and provide new insights into the mechanisms of tumorigenesis, including tumor growth, migration, and invasion." (PMID 30346062, 2019). "Compared with normal tissues, NEAT1 expression was obviously up-regulated in tumor tissues." (PMID 30053878, 2018). "Meanwhile, the expression of NEAT1 and miR-34c in tumor tissues were confirmed that knockdown of NEAT1 in vivo could up-regulate the miR-34c levels." (PMID 29654165, 2018). "Although the NEAT1 inhibition impaired the cell vitality, the simultaneous inhibition of miR-34c could antagonize this effect and restore the cell vitality of tumor cells." (PMID 29654165, 2018). "We then determined whether increased DAG+FFA delivery could rectify the tumor growth defect observed in sh-NEAT1 cells in vitro." (PMID 29764424, 2018). "These dynamic changes in NEAT1 isoform expression may affect the main function of NEAT1 as an oncogene or a tumor suppressor." (PMID 30374364, 2018).